RN7SL273P (RNA, 7SL, cytoplasmic 273, pseudogene)
Gene: Miscellaneous RNA gene on chromosome 6 (37,361,185 to 37,361,483, forward strand). Ensembl gene ENSG00000239953.
Homologues: Orthologues: chimpanzee Metazoa_SRP (98% identical), macaque Metazoa_SRP (92% identical). Paralogues in human: RN7SL1 (80% identical), RN7SL3 (80% identical), RN7SL2 (79% identical), RN7SL566P (79% identical), RN7SL126P (78% identical), RN7SL679P (77% identical), RN7SL743P (77% identical), RN7SL127P (77% identical), RN7SL408P (77% identical), RN7SL122P (77% identical), RN7SL220P (77% identical), RN7SL357P (77% identical), and 705 more.